MIR553 (microRNA 553)
Synonyms: hsa-mir-553; MIRN553
Gene: MicroRNA gene on chromosome 1 (100,281,241 to 100,281,308, forward strand). Ensembl gene ENSG00000207750.
Gene Ontology:
Biological process: miRNA-mediated post-transcriptional gene silencing
Cellular component: RISC complex
Homologues: Orthologues: chimpanzee ptr-mir-553 (100% identical), macaque mml-mir-553 (94% identical).